BRCA1 (BRCA1 DNA repair associated)
Diseases named in the same sentence as BRCA1 in open-access papers (continued):
Sharing a sentence is not in itself a finding about the gene and the disease.
cancer (continued). "Studies have suggested that the clinical use of PARP inhibitors might be extended to malignancies other than BRCA1/2-associated cancers, highlighting the need for evaluating the response of cells with different expression levels of PTEN to PARP inhibition." (PMID 31102368, 2019). "Targeting the poly (ADP-ribose) pathway holds great promise as an approach to anti-cancer therapy, and some success has been met using PARP1/2 inhibitors (PARPiS) to treat cancers harboring defects in the homologous recombination repair pathway, especially BRCA1/2 mutated tumors." (PMID 30459355, 2019). "However, the use of PARP inhibitors is limited to cancer patients with BRCA1/2 mutations, which represent only a small subset of cases." (PMID 30717758, 2019). "Thirdly, our observations that BRCA1-mutated cells are resistant to IFN-γ-mediated cytotoxicity and to STAT1 downregulation could have implications for understanding responses to anti-tumor immunity in BRCA1-mutated cancers." (PMID 31840082, 2019). "Our findings suggest a potential mechanism by which loss of function BRCA1 mutations could alter the response of cancer cells to external stimuli." (PMID 31840082, 2019). "For the first time, we were able to show that high Ubc9 expression due to BRCA1 mutation may trigger an early growth and transformation advantage to normal breast and ovarian epithelial cells resulting in aggressive cancers." (PMID 33860286, 2019). "In Conclusion, mutation of BRCA1 gene varies among population and age of onset of cancer." (PMID 31759379, 2019). "Therefore, the analysis of pathogenic variants, including CNVs, is possible not only in BRCA1/2, but also in an additional 92 further cancer-related genes." (PMID 31029168, 2019). "Finally, by applying a comparative oncogenomics strategy to uncover additional culprits of tumorigenesis, we identified MCL1 as a druggable cancer driver that collaborates with MYC in BRCA1-deficient TNBC." (PMID 30674894, 2019). "Mechanistically, cancers with BRCT domain mutations harbor BRCA1 gene breakpoints within or adjacent to Alu elements in intron 15; producing partial gene duplications, inversions and translocations, and terminating transcription prior to the mutation-containing BRCT domain." (PMID 31827092, 2019). "The cancer-associated genotoxic stress that arises from mutations in BRCA1/2 or members of the FA complex can all be partially rescued through overexpression of RNase H1 in cancer cell lines, suggesting that the aberrant R-loop formation contributes to malignant progression." (PMID 31225499, 2019). "Further studies would, however, be necessary to determine if this potentially evolved mechanism is genetically linked to the BRCA1 or 2 loci and/or results from phenotypic plasticity when an enhanced risk of cancer (e.g., high rate of malignant cell productions) is perceived by the organism." (PMID 31805037, 2019). "Indeed, it has been showed that the synthetic lethality approach using PARP-1 inhibition is maximum in BRCA1/2 deficient cancer patients." (PMID 31717700, 2019). "However, severity of the deleterious effect likely depends on locations of the BRCA1 cancer-predisposing mutations." (PMID 30995943, 2019). "Moreover, MCL1 inhibition potentiates the in vivo efficacy of PARP inhibition (PARPi), underscoring the therapeutic potential of this combination for treatment of BRCA1-mutated cancer patients with poor response to PARPi monotherapy." (PMID 30674894, 2019). "This is one mechanism by which BRCA1/2-deficient cancers are highly sensitized to PARP inhibition, although other functions of PARP may contribute as well." (PMID 31552165, 2019). "Notably, BRCA1/2 mutated cancers exhibited a higher RANKL expression (p = 0.033), but not increased RANK or OPG expression." (PMID 31181781, 2019). "Indeed, as much as half of the HR deficiency in all cancers is due to derangement of factors other than BRCA1/219,30." (PMID 30733539, 2019).
cancer (continued). "The clinical management of BRCA1/2 mutation carriers requires accurate cancer risk estimates." (PMID 30136106, 2019). "Data from the Oncogenetics and Cancer Prevention Unit of the Oncology Service at the Geneva University Hospitals was merged with the Geneva Cancer Registry data to identify women who underwent counselling and were tested for BRCA1 or BRCA2 germline pathogenic variants." (PMID 31491032, 2019). "These are representative known cancer predisposition genes: BRCA1, BRCA2, KRAS and RET." (PMID 31391007, 2019). "This suggests that BFs may have the potential to induce metastasis by transforming themselves if the environment is favorable and also that the CAFs and BRCA1-mutated cancer cells have reciprocal regulatory effects on one another." (PMID 30224826, 2018). "This study describes the cancer characteristics and outcomes of male BRCA1/2 mutation carriers." (PMID 29433453, 2018). "We believe it might be reasonable to interpret the findings that common variants explain as much Σ%FRR of high-risk cancers as BRCA1/2 mutations." (PMID 30323354, 2018). "A third of male BRCA1/2 mutation carriers had a diagnosis of cancer." (PMID 29433453, 2018). "Moreover, cancer risk varies by mutation location within the BRCA1 or BRCA2 genes and family history." (PMID 30518089, 2018). "Deleterious mutations in the BRCA1/2 genes were detected in 13% of each group, while mismatch repair gene mutations were detected in 2.4% and 9.8% of patients with single versus multiple primary cancers respectively." (PMID 30093976, 2018). "Since the identification of BRCA1 pathogenic variants allows for specific preventive and surveillance measures, the establishment of the pathogenicity of BRCA1 variants is crucial for clinical management of cancer patients and family members at risk of breast and ovarian malignancy." (PMID 29996917, 2018). "In summary, our results suggest that BRCA1 polymorphisms may play an important role in the etiology of cancer." (PMID 29492227, 2018). "The presence of the rs16941 polymorphism has been reported to be significantly associated with the positive expression of BRCA1 protein; however, we found that rs16941 could increase cancer risk among Caucasian populations." (PMID 29492227, 2018). "Future prospective studies are needed to determine whether the same psychosocial factors influence the surgical decision making of individuals with hereditary cancer predispositions beyond BRCA1 and BRCA2." (PMID 29733510, 2018). "Interestingly, cancer-predisposing BRCA1 mutants A1708E and M1775R exhibit increased affinity for COBRA1." (PMID 30558184, 2018). "The mechanism underlying the development of cancer due to loss of BRCA1 and BRCA2 has been explained by the ‘caretaker and gatekeeper’ hypothesis." (PMID 29416040, 2018). "Here we show that BRCA1 mutations are associated with a moderate risk (OR, > 2) of PC, even in a series of sensitivity analyses accounting for potential modifying effects of other cancers." (PMID 31497750, 2018). "This type of cancer is more common in women with BRCA1 gene mutations." (PMID 29895744, 2018). "In addition, we have chosen to apply HORMAD1 overexpression model instead of genetic inhibition, as the acute loss of HR repair genes such as BRCA1 have been shown to be toxic to cancer cells." (PMID 30046392, 2018). "Even in cases where the BRCA1 phenotype remains normal, mutations in other key genes that control motility might affect the stroma, resulting in cancer progression." (PMID 30224826, 2018).
cancer (continued). "However, the variant has been shown to result in a lower risk of cancer development than what is typically observed for BRCA1 variants." (PMID 30458859, 2018). "We examined what type of cancer occurred in BRCA1/2 mutation carriers." (PMID 29176636, 2018). "DNA double-strand break repair is a relevant function of BRCA1 for decreased cancer risk." (PMID 29867779, 2018). "Thus, risk assessment in BRCA1/2 mutation carriers is of great importance in clinical service and cancer management." (PMID 29861850, 2018). "Her sister is also a BRCA1 mutation carrier under cancer screening." (PMID 30518416, 2018). "It was generally believed that when the repair of SSBs was blocked by PARP1 inhibition, SSBs would be converted into DSBs in S-phase that can only be repaired by HRR, therefore impaired HRR, as in cancer cells carrying BRCA1 or BRCA2 mutations, would render synthetic lethality with PARP1 inhibition." (PMID 29684820, 2018). "Clinical evidence also suggests that patients with hypermethylation on the promoter region of tumor suppressive genes, such as Ras association domain family member 1 (RASSF1A) 35, BRMS133, and breast cancer type 1 susceptibility gene (BRCA1) 36, 37, 38, are associated with poor prognosis." (PMID 29473320, 2018). "Of the 102 patients who tested positive for a BRCA1/2 mutation, 33 (32%) had a diagnosis of cancer." (PMID 29433453, 2018). "Pathogenic BRCA1/2 mutations are highly penetrant mutations that are inherited in an autosomal dominant fashion and result in a significantly increased risk of breast, ovarian, prostate, melanoma, pancreatic and other cancers." (PMID 29433453, 2018). "Preclinical work from our laboratory demonstrated that in BRCA1-deficient breast cells, oestrogen and its metabolites are capable of driving DNA damage and subsequent genomic instability, which are well-defined early events in BRCA1-related cancers." (PMID 30580266, 2018). "However, only a small fraction of all cancer patients carry a BRCA1 or BRCA-2 deficiency, making PARP inhibitors efficacious in only a limited subset of patients." (PMID 29545922, 2018). "Moreover, BRCA1 deficiency in cancer cells can create oxidative stress in both cancer cells and CAFs along with increased glycolysis in CAFs21,22." (PMID 30224826, 2018). "The neXtProt Cancer variant portal we have developed provides an exhaustive list of BRCA1 variants for which molecular phenotypes are available, curated in a highly structured model, without redundancy in the data and with complete traceability to the original experimental results." (PMID 29996917, 2018). "In particular, it will be interesting to determine whether olaparib resistance in patients with BRCA1/2 mutant cancers can be driven by loss of PARP binding to DNA." (PMID 29670134, 2018). "The cancer characteristics of men with BRCA1/2 mutations are less well studied." (PMID 29433453, 2018). "While it is abundantly clear that germ-line BRCA1 mutations confer tissue- and cell lineage-specific cancer, the mechanism underlying the context-dependent dysfunction of cancer-predisposing BRCA1 mutations remains largely unknown." (PMID 30558184, 2018). "What has emerged is that whereas some germline variants confer high risk for cancer due to disruption of gene function, many BRCA1 and BRCA2 variants identified during routine genetic testing are determined to have little or no clinical significance with respect to cancer risk." (PMID 30586411, 2018). "An effective reduction in the migratory and invasive ability along with reduction in the secretory levels of CCL5 protein in MAF than CAF was also observed with both the inhibitors, suggesting the possibility to attenuate the crosstalk between MAF and BRCA1 mutated cancer cells." (PMID 30224826, 2018). "BRCA1/2 mutations have clinical implications in cancer treatment." (PMID 31608315, 2018).
cancer (continued). "Hence, BRCA1/BRCA2 pathogenic mutations among other hereditary factors appeared to be a more prevalent cancer driver in this younger Asian BC cohort." (PMID 29713003, 2018). "Similar to Lynch syndrome, this example raises the question of whether constitutional BRCA1/2 epimutations can represent an alternative mechanism for cancer predisposition." (PMID 30453575, 2018). "iPARP cause HRR leading gene-deficient (including BRCA1/2) cancer cells to die by apoptosis." (PMID 30103829, 2018). "The incidence of cancer in 37 unaffected BRCA1/2 mutation carriers was also examined." (PMID 29176636, 2018). "Based on this information, we expected that mutations of BRCA1 might subsequently result in the adaptation of cancer cells by reciprocally altering their stroma to facilitate dissemination to distant sites." (PMID 30224826, 2018). "Out of the 56 DV-positive individuals with a family history of HBOC-associated cancers, only 32% (n = 18) were found to have DV in BRCA1/2 and of the 47 DV-positive individuals with a family history of LS-associated cancer, only 21% (n = 10) carry DV in LS genes." (PMID 29308099, 2018). "Therefore, PARP inhibitors have been proposed as new therapeutic strategies for human malignant tumors carrying mutations in BRCA1/2 genes." (PMID 29784019, 2018). "PARPi may also be relevant as targeted therapy for cancers with a range of defects in HR DNA repair beyond BRCA1/2 mutation." (PMID 30266954, 2018). "At which extend a cancer predisposing protein truncating mutation (e.g., in BRCA1 or BRCA2) will impair DNA surveillance complexes can also depend on the presence of particular polymorphic forms in other proteins participating in the same complexes (called modifier genes in this case)." (PMID 28649653, 2017). "This suggests that loss of 53BP1 expression may be an accompanying molecular change and may be required for the BCCIP-deficient benign lesions to evolve into malignant tumors, which would resemble the relationship between BRCA1 and 53BP1 in tumor development." (PMID 29047390, 2017). "Depleting RAD52 can cause synthetic lethality in BRCA1/2 mutant cancers by an unknown molecular mechanism." (PMID 29145865, 2017). "Beyond its well-recognized bone-targeted activity impeding osteoclastogenesis, denosumab has been proposed to interfere with the cross-talk between RANKL-producing sensor cells and cancer-initiating RANK+ responder cells that reside within premalignant tissues of BRCA1-mutation carriers." (PMID 28388533, 2017). "As disulfiram is in widespread clinical use, its safety and tolerability are well established and it could be rapidly reassigned for treatment of cancers associated with BRCA1/2 mutations." (PMID 28729482, 2017). "In conclusion, despite several limitations, this meta-analysis suggested that BRCA1 P871L genetic variation may be associated with decreased susceptibility to cancer." (PMID 28427168, 2017). "In conclusion, this comprehensive meta-analysis suggests that BRCA1 P871L polymorphism may be associated with decreased susceptibility to cancer." (PMID 28427168, 2017). "We then investigated whether aNHEJ was the escape pathway utilized by the EEPD1/RAD52 co-depleted BRCA1-deficient cancer cells for survival." (PMID 29145865, 2017). "Importantly, many cancers harbor defects in double-strand break repair pathway genes, like BRCA1 and BRCA2, that encode functions within the homologous recombination repair (HRR) pathway." (PMID 29104272, 2017). "Currently, malignant tumors harboring BRCA1/2 mutations are those selected for PARPi treatment but emerging evidence suggests that also tumors with defects in other components of DNA damage pathways may benefit from these drugs." (PMID 28881597, 2017). "Several HR proteins are mutated in cancer, including BRCA1/2 in breast and ovarian cancer." (PMID 28058462, 2017).
cancer (continued). "As expected, PPV was better in BRCA1/2 carriers (42.9%) than in women who had an unknown mutation status (7.7%) because of the lower cancer incidence in women with an unknown status." (PMID 28240969, 2017). "This loss of 53BP1 in BRCA1-associated cancers may result in resistance to PARP inhibitors and platinum agents." (PMID 28412751, 2017). "Patients with BRCA1/2 mutated cancers have better outcome following platinum-based chemotherapy than their non-BRCA1/2 mutated counterparts as their cells are incapable of repairing DNA double-strand breaks (DSBs), leading to sensitization to DNA-damaging agents." (PMID 28117679, 2017). "Notably, however, cancer cells with defects in HR (most commonly arising from mutations of BRCA1 and BRCA2 proteins) have exhibited vastly increased sensitivity to PARP-1 inhibitors." (PMID 28058462, 2017). "Together the findings reveal previously unknown effects of certain variants that are commonly seen in cancer patients as well new insights into how the BRCA1 protein repairs DNA." (PMID 28398198, 2017). "Common genetic variants modify cancer risks for female carriers of BRCA1/2 mutations." (PMID 28448241, 2017). "Indeed, cancer cells harboring mutations in BRCA1 suffer from genomic instability and increased DNA lesions." (PMID 28262780, 2017). "However, identification of a hereditary BRCA1/BRCA2 mutation in a family is often via initial diagnostic testing in an individual with cancer." (PMID 28780755, 2017). "PARP inhibitors profoundly sensitize cancer cells to DNA damaging agents and act through synthetic lethality in cells with defects in homologous recombination (HR) DNA repair caused by molecular aberrations such as BRCA1/2 mutations." (PMID 28829366, 2017). "Although the etiology of OC is not yet fully understood, certain factors, including age, late childbearing, early onset at menarche, late menopause, and breast cancer 1 (BRCA1) and breast cancer 2 (BRCA2) mutations, are implicated in OC formation and development." (PMID 27835912, 2017). "Noteworthy, HOXA11 and BRCA1 cancer associated genes were demethylated after treatment." (PMID 28008141, 2017). "We specifically sought to assess if there was a higher frequency of RDR with PARP inhibitor treatment in patients with germline BRCA1/2 mutation cancers versus those with wildtype or unknown BRCA1/2 mutation status." (PMID 29262651, 2017). "Since β-hCG is itself secreted by BRCA1 mutated cancers, it could have an autocrine effect in inducing tumorigenesis of such cancers." (PMID 28869585, 2017). "While treating patients with advanced solid tumors with single agent PARP inhibitors within the context of early phase clinical trials, we observed an anecdotally high frequency of patients with RDR on treatment, including those with germline BRCA1/2 mutation cancers." (PMID 29262651, 2017). "Indeed, RAD51 has been demonstrated to be an alternative synthetic lethal target in BRCA1-mutated cancers." (PMID 27507046, 2016). "This is in line with the fact that some tumors, lacking germline mutations in BRCA1 show a BRCAness phenotype, implying that they could have a cancer progression program similar to BRCA1 mutated tumors." (PMID 26979459, 2016). "Therefore, BRCA1/2-mutated cancers treated with PARP inhibitor show synthetic lethality by the severe defect in DNA repair." (PMID 26927065, 2016). "We propose that mutations in the cancer susceptibility genes BRCA1/2 might trigger “accelerated geroncogenesis” in breast and ovarian epithelia." (PMID 26943589, 2016). "There are limited data on the use of alkylating cytotoxic drugs in BRCA1/2-mutated cancers." (PMID 27555886, 2016).